EMILIN1 (elastin microfibril interfacer 1)
Diseases named in the same sentence as EMILIN1 in open-access papers (continued):
Sharing a sentence is not in itself a finding about the gene and the disease.
tumor (continued). "This is also in line with the observed localization of EMILIN1, deposited in the ECM that surrounded the normal mammary ducts and the tumor masses, while being completely absent within the tumors." (PMID 38184660, 2024).
cancer (21 papers, 2017 to 2026). A tumor composed of atypical neoplastic, often pleomorphic cells that invade other tissues. "Knockdown of EMILIN-1 in HNSCC cancer-associated fibroblasts induced cell proliferation and migration." (PMID 39892781, 2025). "This review summarizes the current knowledge on EMILIN-1 in cancer, focusing on its dual function as an active extracellular matrix regulator of intercellular signaling." (PMID 40643467, 2025). "EMILIN-1 has emerged as a promising biomarker in oncology, supported by its frequent identification in cancer-related gene expression signatures." (PMID 40643467, 2025). "The conditioned medium from EMILIN-1 knockdown cancer-associated fibroblasts increased HNSCC cell proliferation, and the co-culture system enhanced cancer cell migration and invasion." (PMID 39892781, 2025). "Initially identified for its involvement in elastogenesis and vascular homeostasis, EMILIN-1 has gradually emerged as a key player in cancer biology." (PMID 40643467, 2025). "EMILIN1, an extracellular matrix (ECM) glycoprotein, has been implicated in cancer progression and metastasis." (PMID 39958347, 2025). "Focusing on p16-negative cases, they showed that a multivariate logistic regression model comprising ITPR3, KMT2D, EMILIN1, and patient’s age can accurately predict second cancer occurrence with 88% sensitivity and 75% specificity." (PMID 34771648, 2021). "The expression of EMILIN-1 varies across different cancer types." (PMID 39892781, 2025). "Notably, EMILIN-1 expression is frequently reduced or its structure altered by proteolytic degradation in advanced cancers, correlating with disease progression and poor prognosis." (PMID 40643467, 2025). "EMILIN1 is an ECM glycoprotein, whose function has been linked to cancer and metastasis." (PMID 38184660, 2024). "However, the expression of the PDGFRA, PDGFRB, CDH11, and EMILIN1 genes was mainly reduced in fibroblasts after co-cultivation with cancer cells." (PMID 36263012, 2022). "EMILIN-1 has been characterized in multiple scenarios such as cell migration and proliferation, cell migration, lymphatic vessel function skin homeostasis, and cancer development." (PMID 34299025, 2021). "What if any role is played by EMILIN1 in cancer remains uncertain." (PMID 31242895, 2019). "Thus, the suppression of cell cycle pathway–related genes and PI3K/AKT may be partially attributed to EMILIN-1's effect on cell proliferation and other cancer-related processes, such as migration and invasion." (PMID 39892781, 2025). "Both EMILIN1 and FSTL1 exert contrasting effects in different types of cancer probably because both interact with TGF-β which is a paradigm of duality in cancer (Massagué, 2008)." (PMID 29740513, 2018). "Moreover, the CM from EMILIN-1 knockdown CAF increased the proliferation of HNSCC cancer cells, whereas the co-culture system enhanced cancer cell migration and invasion." (PMID 39892781, 2025). "Furthermore, when co-culturing EMILIN-1 knockdown CAF3 and cancer cells using a Transwell insert system, FaDu and CAL27 cells in the upper chamber showed increased cell migration (P < 0.001) and invasion (P < 0.05)." (PMID 39892781, 2025). "There is controversy about the roles of EMILIN1 and FSTL1 in cancer." (PMID 29740513, 2018). "Therefore, we have highlighted the role of EMILIN1 and TSPAN9 in cancer progression." (PMID 31242895, 2019). "Interestingly, these two modules contain three common mRNAs (EMILIN1, COL1A2, ENC1) and one of them (COL1A2) is related to cancer, suggesting that these modules (e.g. modules 15 and 17, modules 31 and 32 in OV) with many overlaps of mRNAs are more likely to have similar biological functions." (PMID 30732558, 2019). "We also noted a change in the expression level of 3 genes (PDGFRB, EMILIN1 and ASPN) during cultivation of the primary cell line of skin fibroblasts in the absence of cancer cells for 4 weeks." (PMID 36263012, 2022).
connective tissue disease (5 papers, 2017 to 2025). "Mutations in elastin microfibril interface-located protein 1 (EMILIN1) are linked to a range of connective tissue disorders, involving the vascular system, skeletal structures, and possibly the nervous system." (PMID 40909027, 2025). "Our research utilised the same overlapping genes and elicited the same novel genes for both EMILIN1-related Connective Tissue Disease and Lethal Arteriopathy Syndrome due to Fibulin-4 deficiency." (PMID 39480826, 2024). "EMILIN1-related Connective Tissue Disease is caused by the EMILIN1 gene and affects fewer than one in a million people." (PMID 39480826, 2024). "Defects in EMILIN1 expression adversely affect lamellar structure and function and increase aortic wall inflammation and have been associated with connective tissue disease)." (PMID 35052463, 2022). "In this context, the discovery of a new and direct link between fibulin-4 and EMILIN-1 in the ECM produced by osteoblasts provides a better molecular understanding of pathogenic mechanisms underlying connective tissue disorders caused by mutations in fibulin-4 and EMILIN-1." (PMID 28717224, 2017). "We therefore investigated the spatiotemporal localization of EMILIN-1, -2, -3 in human skin induced by aging, UV-exposure, fibrosis, and connective tissue disorder." (PMID 39639116, 2024). "We propose that MYH11 and SYNPO2 are novel genes in EMILIN1-related Connective Tissue Disease with both contributing to presentations common to this disorder and Lethal Arteriopathy Syndrome due to Fibulin-4 Deficiency." (PMID 39480826, 2024).
infection (3 papers, 2020 to 2025). The state of being infected such as from the introduction of a foreign agent such as serum, vaccine, antigenic substance or organism. "In female samples, no gene was found to be regulated at all investigated time points, whereas one down-regulated gene (Zinc finger protein 704 (ZNF704)) and two up-regulated genes (EMILIN1, IL7R) were found over the total course of infection in male samples." (PMID 40794782, 2025). "Therefore, EMILIN1 and LYZ may be closely related to the pathogenesis of BD and the regulation of infection and inflammation, potentially playing positive and active anti-inflammatory roles." (PMID 39687011, 2024).
cardiovascular disease (2 papers, 2014 to 2017). "Mutations in human EMILIN1 have been associated with cardiovascular disease, but not specifically AVD or aortopathy, and therefore could represent an important candidate gene and/or genetic modifier." (PMID 25056700, 2014).
EMILIN1 also shares sentences with these, for which no sentence is quoted: Marfan syndrome (2 papers); neuroblastoma (2); Obesity (2); anaplastic astrocytoma (1); anaplastic oligoastrocytoma (1); anemia (1); Arthritis (1); astrocytoma (1); autoimmune disease (1); Cerebellar atrophy (1); CNS tumors (1); colitis (1); Duchenne muscular dystrophy (1); epilepsy (1); essential hypertension (1); glioma (1); hepatic carcinomas (1); Hepatic fibrosis (1); Hereditary Motor Sensory Neuropathy (1); hyperglycaemia (1); Insulin resistance (1); Intellectual disability (1); liver cancer (1); lymph node metastasis (1); mesothelioma (1); movement disorder (1); muscular disorders (1); oligoastrocytoma (1); oligodendroglioma (1); ovarian serous tumor (1).
A further 6 diseases each share a sentence with EMILIN1 in 1 paper.